SST (somatostatin)
Diseases named in the same sentence as SST in open-access papers (continued):
Sharing a sentence is not in itself a finding about the gene and the disease.
type 1 diabetes (11 papers, 2018 to 2025). "Impaired somatostatin secretion owing to loss of β- to δ-cell electrical coupling underlies defective counter-regulatory glucagon secretion in type-1 diabetes." (PMID 39313541, 2024). "The higher number of alpha cells directly adherent to delta cells in type 1 diabetes likely increases the alpha cells’ exposure to somatostatin." (PMID 40473678, 2025). "In type 1 diabetes there are more alpha cells directly adherent to delta cells, likely increasing the alpha cells’ exposure to somatostatin which inhibits glucagon secretion." (PMID 40473678, 2025). "The somatostatin-positive cell area and somatostatin staining intensity were elevated in islets from donors with recent-onset type 1 diabetes." (PMID 39404844, 2024). "One unexpected outcome of this study was that we also noted the presence of MDA5 positive, but somatostatin/insulin/glucagon immunonegative cells in type 1 diabetes cases." (PMID 35957810, 2022). "Therefore, we analysed the somatostatin-positive area in islets and found that both delta cell area and somatostatin staining intensity are increased in donors with recent-onset type 1 diabetes." (PMID 39404844, 2024). "Islet somatostatin expression levels also varied among donors, and the median fluorescence intensity of somatostatin in islets was comparable between non-diabetic donors and donors with type 1 diabetes." (PMID 39404844, 2024). "Interestingly, the median somatostatin-positive area was significantly elevated in islets from donors with short-duration type 1 diabetes (4.68% vs 11.12% for non-diabetic donors vs donors with short-duration type 1 diabetes, respectively)." (PMID 39404844, 2024). "Short-term dapagliflozin treatment in type 1 diabetes increases plasma ketone concentrations without affecting the secretion of GLP-1, glucagon or somatostatin." (PMID 40629004, 2025).
pituitary tumor (10 papers, 2013 to 2025). A benign or malignant neoplasm affecting the pituitary gland. "GH3 and GH4C1 represent the most widely used GH-secreting pituitary tumor cell lines for the studies of the somatostatin network." (PMID 34128215, 2022). "Pituitary tumors with reduced AIP expression are reported to be frequently resistant to first-generation somatostatin analogs." (PMID 27706259, 2016). "A therapeutic trial that could sensitize ACTH-secreting pituitary tumors to endogenous somatostatin prior to surgery could be beneficial, particularly in patients with invasive macroadenomas." (PMID 35058882, 2021).
temporal lobe epilepsy (10 papers, 2014 to 2023). A localization-related (focal) form of epilepsy characterized by recurrent seizures that arise from foci within the temporal lobe, most commonly from its mesial aspect. "For example, selective loss or damage to PV and SST interneurons characterizes temporal lobe epilepsy." (PMID 29615590, 2016). "In contrast, in the dentate gyrus, somatostatin reduction occurs in genetic models of temporal lobe epilepsy." (PMID 37730546, 2023). "In particular, the dorsal dentate gyrus and CA3 somatostatin-positive neurons and dorsal lateral septum cholecystokinin-positive neurons are selectively vulnerable to damage after temporal lobe epilepsy." (PMID 35571372, 2022). "Stereological quantification of VIP/CR cells in a model of temporal lobe epilepsy demonstrated that they survive in epileptic mice, despite a reduction in their somatostatin-expressing (Som) cell targets." (PMID 34819310, 2021). "In tissue from patients with temporal lobe epilepsy (TLE), hippocampal seizure foci were characterized by the loss of somatostatin (SST)+ interneurons." (PMID 29997478, 2018).
autism (9 papers, 2018 to 2025). Persistent deficits in social interaction and communication and interaction as well as a markedly restricted repertoire of activity and interest as well as repetitive patterns of behavior. "We chose to focus our investigation on SST-INs in CA1 because of their known roles in the aetiology of autism-associated phenotypes in rodent models (see Discussion) and experimental tractability." (PMID 36658491, 2023). "Across the germinal zones, autism genes associated with transcriptional regulation showed peak expression in neural progenitors in the medial ganglionic eminences, the primary origin of parvalbumin- and somatostatin-expressing interneurons." (PMID 41279531, 2025). "We identified 710 SNPs in these lines that indicate new potentially important genes for FP such as TMPRSS6 (implicated in autism), and SST and ARNT2 (somatostatin function)." (PMID 39702044, 2024). "Similar to our finding of reduced SST in the APC cKO mPFC, two other studies suggest that SST interneuron dysfunction may link to autism-like behaviors." (PMID 30369876, 2018). "In this study, we provide morphological evidence that abnormal accumulation of N-tr-Aβ with and without pyroglutamate-11 modified N-terminus in autism affects mainly the subpopulation of GABAergic neurons expressing parvalbumin, but not those expressing somatostatin." (PMID 32345355, 2020).
Insulin resistance (9 papers, 2012 to 2025). Increased resistance towards insulin, that is, diminished effectiveness of insulin in reducing blood glucose levels. "T2D has been linked with alterations in several of these regulatory mechanisms, including increased alpha‐cell insulin resistance, elevated circulating somatostatin levels, and at least in animal models, somatostatin hypersecretion." (PMID 36056607, 2022). "In terms of insulin for the treatment of T2DM, a study by Haider showed that insulin or somatostatin infusion suppressed glucose-induced elevation of visfatin (a novel insulin-mimetic adipocytokine), which can reduce fat accumulation and insulin resistance in patients with T2DM." (PMID 35495951, 2022). "On the contrary, lowering insulin below fasting levels with somatostatin reduced BGM in metabolically healthy individuals but significantly less in insulin resistance." (PMID 39185744, 2025). "Likewise, the underlying molecular mechanisms as well as the precise role and the contribution of islet derived-SST, -CORT, and -ghrelin in the pancreatic endocrine deregulation and/or the resulting insulin resistance under severe metabolic conditions should be investigated." (PMID 23162532, 2012).
pancreatic neuroendocrine tumor (9 papers, 2013 to 2025). Pancreatic endocrine tumor, also known as pancreatic neuroendocrine tumor (PNET), describes a group of endocrine tumors originating in the pancreas that are usually indolent and benign, but may have the potential to be malignant. "It has been demonstrated that pancreatic NET metastases express lower levels of somatostatin, and the knockdown of somatostatin in pancreatic NET cell lines increases metabolic activity, viability, and growth." (PMID 35163374, 2022). "The conclusion of this study is that epidrug treatment might hold promise for improving and adding to current somatostatin agonist treatment strategies of patients with pancreatic NETs." (PMID 35158852, 2022). "The five patients who had true positive elevated plasma somatostatin concentrations all had pancreatic NETs, but none of them had confirmed MEN1." (PMID 33391185, 2020).
cervical cancer (8 papers, 2008 to 2024). A primary or metastatic malignant neoplasm involving the cervix. "We tested for DNA hypermethylation in promoter regions of GHSR, SST, and ZIC1, which enables the accurate detection of both bladder and cervical cancer in urine." (PMID 33572525, 2021). "Urine samples (27 controls, 30 CIN3 and 17 cervical cancer) were processed into 3 fractions and tested for 5 methylation markers (ASCL1, GHSR, LHX8, SST, ZIC1)." (PMID 32171935, 2020).
neuroblastoma (8 papers, 2016 to 2023). Neuroblastoma (NB) is the most common solid, extracranial childhood tumor. "In addition, high levels of SST in plasma or tumors are detected in neuroblastoma." (PMID 36851385, 2023). "Due to the cytotoxic and cytostatic effects of somatostatin, the expression of SSTRs has been found to inversely correlate with MYCN amplification and to positively correlate with survival of patients with differentiated neuroblastomas." (PMID 30018737, 2018). "We also demonstrated that somatostatin is likely to increase the level of IDE but not NEP in neuroblastoma cells." (PMID 27096746, 2016).
paraganglioma (8 papers, 2014 to 2026). A benign or malignant neoplasm arising from paraganglia located along the sympathetic or parasympathetic nerves. "Tumor size and grade may help predict metastatic potential, while the relatively frequent paraganglioma-like morphology, often associated with diffuse somatostatin expression, can represent a diagnostic pitfall." (PMID 42274928, 2026). "In previous investigations of paragangliomas quite different findings with respect to the expression pattern and the intensity of expression of individual SST subtypes were reported." (PMID 29163802, 2017). "In our study, SST2A was the most significantly expressed SST in the paragangliomas investigated, followed by SST5 and the other SSTs, which were clearly of secondary importance." (PMID 29163802, 2017). "The fasting serum level of somatostatin is usually increased in this pathology, but this dosage is not specific because somatostatin also increases in pheochromocytoma, lung cancer, medullary thyroid carcinoma or paraganglioma." (PMID 37628857, 2023). "Thus, a number of studies have already been performed assessing SST expression also in paragangliomas, both at the mRNA and at the protein level." (PMID 29163802, 2017). "In view of the contradictory results in literature, in the present study the SST expression pattern was re-evaluated in a large set of paragangliomas, differentiating between parasympathetic and sympathetic tumors, primary tumors and metastases, and SDHB positive and negative cases." (PMID 29163802, 2017). "The diagnostic accuracy of 68Ga-SST-analogues PET/CT is superior to 131I-MIBG; thus, in the case of negative 123I-MIBG scan in patients with a high pretest probability of phaeochromocytoma or paraganglioma, 68Ga-labeled SST-analogues PET/CT should be considered." (PMID 24693229, 2014). "We then compared theexpression of somatostatin to the histopathological analysis of the surgicalspecimens, in order to assess the sensitivity and specificity of SRS for thediagnosis of paraganglioma." (PMID 34866696, 2021). "In the present study, expression of all five somatostatin receptor (SST) subtypes, chemokine receptor CXCR4 and endothelin receptor type A (ETA) was assessed by means of immunohistochemistry in a total of 66 paraffin-embedded paraganglioma samples from 55 patients." (PMID 29163802, 2017).
Hypertension (7 papers, 2013 to 2025). The presence of chronic increased pressure in the systemic arterial system. "However, some ganglioneuromas may be also functional and secrete peptides, such as VIP and somatostatin, causing diarrhea, hypertension, and sweating." (PMID 35273997, 2022). "Nevertheless, the association with adverse cardiovascular outcome of endothelin-1 and somatostatin, related to hypertension and hormone regulation, respectively, was modified by sex in the current study." (PMID 37198662, 2023). "In one study, somatostatin was designated as a target for hypertension and hyper-glycerolemia with linkage analysis following genome-wide microsatellite marker scan of 38 families." (PMID 35571045, 2022). "Among the highly down-regulated genes in the MCA of the hypertension group were SST, ADAM6, and PRLR." (PMID 23874591, 2013).
medullary thyroid carcinoma (7 papers, 2013 to 2023). "Liver cirrhosis and medullary carcinoma of the thyroid therefore appear to be the two main conditions for which several studies have reported an association with elevated fasting plasma somatostatin concentrations." (PMID 33391185, 2020). "Several studies have suggested that elevated circulating concentrations of somatostatin can be found in patients who have cirrhosis or medullary carcinoma of the thyroid." (PMID 33391185, 2020). "The receptor of SST was reported to be a predictor of better response to therapy in medullary thyroid carcinoma." (PMID 29740512, 2018). "Publications have been retrieved in MEDLINE at Pubmed (there is no fix date retrospectively) up to October 2012 using the terms “medullary thyroid carcinoma”, “somatostatin”, “pregnancy” and “incretins”." (PMID 23514614, 2013). "SST-positive cells are frequently seen in medullary thyroid cancer in contrast to no expression in normal thyroid." (PMID 38203605, 2023).
portal hypertension (7 papers, 2004 to 2024). Increased blood pressure in the portal venous system. "The neuropeptide hormone somatostatin administered exogenously has caused a reduction in portal hypertension and variceal bleeding in patients suffering from liver cirrhosis." (PMID 15596012, 2004). "In fact, for many years, somatostatin analogs have been used in the treatment of portal hypertension by inducing vasoconstriction of the splanchnic vasculature." (PMID 31136617, 2019). "The role of glucagon in the splanchnic hyperemia of portal hypertension provides a rationale for the use of somatostatin and its synthetic analogs to reduce glucagon level, thereby treating portal hypertension." (PMID 22666604, 2012). "β-Blockers, somatostatin analogues, and vasopressin have been used to reduce portal hypertension." (PMID 39512771, 2024). "Previous animal studies suggested that somatostatin may affect portal HBF and portal pressure primarily in the presence of portal hypertension." (PMID 32962657, 2020).
esophageal cancer (6 papers, 2015 to 2023). A primary or metastatic malignant neoplasm involving the esophagus. "Increased methylation in the SST promoter region, causing gene silencing, was evinced in human esophageal carcinomas, and it also occurs early in Barrett-associated esophageal adenocarcinogenesis." (PMID 25723531, 2015). "Previous studies have shown the abnormal DNA methylation of the SST in the head and neck squamous cell carcinoma, pancreatic ductal adenocarcinoma, and esophageal cancer and found downregulation of the SST in the GC tissues." (PMID 35242243, 2022). "The results of the methylation test showed that the SST gene was up-regulated a large number, which may be a key gene involved in methylation modification to regulate the progression of esophageal cancer." (PMID 32068233, 2020). "Interestingly, it was later reported that two CpG sites within SST’s first exon could detect colorectal, gastric, and esophageal cancer with 59.3% sensitivity and 72.8% specificity using tissue samples of 229 patients." (PMID 36980276, 2023). "However, the patterns of the SST methylation and expression in esophageal cancer (EC) are not clear." (PMID 35242243, 2022).
glioblastoma (6 papers, 2002 to 2025). The most malignant astrocytic tumor (WHO grade IV). "Furthermore, analysis of glioblastoma multiforme tissue samples demonstrated both SST hypermethylation on CpG sites and a 80.5-fold downregulated SST expression level compared to control brain tissue." (PMID 33085037, 2021). "Somatostatin receptors (SSTR) are a family of integral membrane glycoproteins, that have been effectively targeted using SST agonists and antagonists in different cancer types, including neuroblastoma, meningioma, low-grade gliomas and glioblastoma multiforme (GBM)." (PMID 31374991, 2019). "In addition, we demonstrated that the presence of receptors for somatostatin on U-87MG human glioblastomas can be utilised for an improvement in therapeutic efficacy when the targeted cytotoxic somatostatin analogue AN-238 which contains AN-201 is used, but not its counterpart containing DOX." (PMID 11953892, 2002). "A clear downregulation of the whole somatostatin/cortistatin-system (except for SSTR5) in glioblastoma vs. non-tumour brain samples was demonstrated, with high discriminatory capacity." (PMID 40268793, 2025).
hepatocellular carcinoma (6 papers, 2014 to 2021). A malignant tumor that arises from hepatocytes. "Similar to somatostatin, SSAs can induce cell cycle arrest by stopping the hepatoma cells in the G1 phase, through specific receptors and the corresponding signaling pathways." (PMID 34873567, 2021). "Other hormones that may cause paraneoplastic diarrhea include glucagon (glucagonoma), gastrin (gastrinoma or hepatocellular carcinoma), somatostatin (somatostatinoma or pheochromocytoma), and the prostaglandins (hepatocellular carcinoma)." (PMID 29177551, 2018). "The positive impact of SST analogue therapy on hepatocellular carcinoma (HCC) is not clear." (PMID 25723531, 2015).
Hyperinsulinemia (6 papers, 2017 to 2025). An increased concentration of insulin in the blood. "Long-acting glucagon preparations, such as zinc protamine glucagon, have been used to treat glucagon deficiency states or in combination with somatostatin to address congenital hyperinsulinemia." (PMID 40119223, 2025). "In HFD-fed rats, due to the infusion of somatostatin inhibiting their hyperinsulinemia, insulin levels during the clamp steady-state were low and close to the baseline levels of control rats." (PMID 39562740, 2025). "As demonstrated in preclinical studies, hyperinsulinemia suppresses pulsatile GH secretion by inhibiting somatotroph function and enhancing somatostatin release, thereby reducing GH bioavailability." (PMID 41282298, 2025).
Sepsis (6 papers, 2020 to 2024). Sepsis is defined as life-threatening organ dysfunction caused by a dysregulated host response to infection. "NF-κB is closely associated with the progress of sepsis and sepsis-induced intestinal barrier dysfunction; thus, we were interested in that whether the NF-κB pathway could be regulated by SST." (PMID 33376482, 2020). "The aim of this study was to investigate the effect of PTX on gastric mucosa PC synthesis, leukocyte infiltration, arachidonic acid-related metabolites, inflammation, oxidative stress, NO, CO, and somatostatin in a rat model of LPS-induced sepsis." (PMID 39765810, 2024). "The specific SST receptor SSTR5 in the intestinal barrier was detected increased by SST in mice with sepsis in this research, so we inferred that SST/SSTRs probably activated the anti-inflammation pathway in septic mouse." (PMID 33376482, 2020). "Furthermore, somatostatin (SST) repaired sepsis-induced intestinal barrier dysfunction through suppression of NF-κB signaling." (PMID 38187112, 2023). "After sepsis control and achieving hemodynamic stability, the enterocutaneous fistula was managed with parenteral nutrition, proton pump inhibitors, anti-cathartics, and somatostatin analogs." (PMID 33395857, 2020). "LPS-induced sepsis changed the gastric mucosal barrier by reducing its phospholipid content, PGI2, and somatostatin levels, as well as increasing MPO, TXB2, LTB4, PLA2, and MDA." (PMID 39765810, 2024).
carcinoid syndrome (5 papers, 2014 to 2025). "In TELESTAR and TELECAST phase III studies, patients with carcinoid syndrome received telotristat ethyl 250 or 500 mg 3 times per day (tid) or placebo tid in addition to somatostatin analogs." (PMID 32146619, 2021). "SST analogues are widely used to treat patients with NETs, as the SST analogues both alleviate the carcinoid syndrome and inhibit growth of the tumors." (PMID 29973528, 2018). "First-line somatostatin analogs (SSAs) provide both antisecretory and antiproliferative effects for SSTR-positive tumors or carcinoid syndrome, with emerging utility in indolent pulmonary carcinoids." (PMID 41333794, 2025). "Whether SST analogs and IFN show a synergistic effect on tumor growth and in carcinoid syndrome symptom management is matter of debate." (PMID 24570674, 2014).